MRC1 (mannose receptor C-type 1)
Diseases named in the same sentence as MRC1 in open-access papers (continued):
Sharing a sentence is not in itself a finding about the gene and the disease.
sarcoidosis (6 papers, 2010 to 2023). Sarcoidosis is a multisystemic disorder of unknown cause characterized by the formation of immune granulomas in involved organs. "The aim of this study was to investigate potential associations of genetic variants in the MRC1 gene with sarcoidosis." (PMID 21029423, 2010). "Of interest, recent genome-wide association analyses have shown that 10p12, where MRC1 is situated, is a susceptibility locus for the development of sarcoidosis." (PMID 21029423, 2010). "Nine single nucleotide polymorphisms (SNPs), encompassing the MRC1 gene, were genotyped in a total of 605 Japanese consisting of 181 sarcoidosis patients and 424 healthy controls." (PMID 21029423, 2010). "This is the first study to imply that genetic variants in MRC1, a major member of the C-type lectin, contribute to the development of sarcoidosis." (PMID 21029423, 2010). "In the present study we demonstrated the association between MRC1 polymorphisms and risk of sarcoidosis in Japanese population." (PMID 21029423, 2010). "We therefore speculated that the MRC1 gene may be an excellent candidate for susceptibility to sarcoidosis, and tested for associations between MRC1 polymorphisms and the development of sarcoidosis in our Japanese case-control analysis." (PMID 21029423, 2010). "However, further studies are clearly needed to achieve a comprehensive coverage of genetic variants in and around the MRC1 gene, in order to identify causal variants conferring susceptibility to an increased risk of sarcoidosis." (PMID 21029423, 2010). "This study suggests that the MRC1 gene may represent an important susceptibility locus for sarcoidosis at chromosome 10p12 and genetic variants in MRC1 may play significant roles in the pathogenesis of sarcoidosis." (PMID 21029423, 2010). "Thus, our current results provide a basis for further identification of the causative variants underlying the relationship between MRC1 gene sequences and sarcoidosis." (PMID 21029423, 2010). "Thus, findings of the current study suggest that MRC1 gene variants may contribute to the development of sarcoidosis." (PMID 21029423, 2010). "Importantly, the association we observed between MRC1 polymorphisms and sarcoidosis adds further evidence for the involvement of macrophage PRRs in the development of a number of chronic inflammatory diseases, including sarcoidosis." (PMID 21029423, 2010). "In support of this, the association of one SNP (rs691005) was confirmed considering for multiple testing and Bonferroni correction, suggesting MRC1 gene as a plausible candidate gene for development of sarcoidosis." (PMID 21029423, 2010).
Hypertension (5 papers, 2016 to 2025). The presence of chronic increased pressure in the systemic arterial system. "This is of particular relevance in the setting of hypertension in which we have demonstrated the accumulation of M2 macrophages, as indicated by expression of the marker CD206 (also known as MRC-1), in the vessel wall associated with aortic stiffening and increased collagen deposition." (PMID 31815149, 2019).
pancreatic ductal adenocarcinoma (5 papers, 2019 to 2025). An infiltrating adenocarcinoma that arises from the epithelial cells of the pancreas. "For example, in pancreatic ductal adenocarcinoma, the knockdown of CCCTC-binding factor (CTCF) resulted in the downregulation of specific biomarkers of M2-like tumor-associated macrophages (TAMs), such as Mrc1 and CD163, reducing invasion and metastasis capabilities." (PMID 39033109, 2024).
pneumonia (5 papers, 2020 to 2024). An acute, acute and chronic, or chronic inflammation focally or diffusely affecting the lung parenchyma, caused by an infection in one or both of the lungs (by bacteria, viruses, fungi, or mycoplasma.). "siRNA knockdown of MRC‐1 or treatment with an anti‐MRC‐1 antibody increased the TNF response to Ply‐expressing S. pneumoniae from DCs and ex vivo alveolar macrophages, as well as in a mouse model of pneumonia." (PMID 35835695, 2022).
tuberculosis (5 papers, 2011 to 2023). A chronic, recurrent infection caused by the bacterium Mycobacterium tuberculosis. "Mrc1 is a pattern recognition receptor that is involved in the identification, binding, and endocytosis of pathogens, including bacteria involved in tuberculosis (Mycobacterium tuberculosis) and meningitis (Streptococcus pneumoniae) and fungi such as Candida albicans." (PMID 31696318, 2020).
autoimmune disease (4 papers, 2020 to 2022). A disorder resulting from loss of function or tissue destruction of an organ or multiple organs, arising from humoral or cellular immune responses of the individual to their own tissue constituents. "This inhibitory effect of T cells by MRC1 has been proposed as a possible therapeutic strategy to downregulate the excessive immune response of autoimmune diseases." (PMID 33092534, 2020).
chronic obstructive pulmonary disease (4 papers, 2014 to 2025). A chronic and progressive lung disorder characterized by the loss of elasticity of the bronchial tree and the air sacs, destruction of the air sacs wall, thickening of the bronchial wall, and mucous accumulation in the bronchial tree. "Recently, MRC1-expressing macrophages have been found to be associated with various diseases, including severe chronic obstructive pulmonary disease, inflammatory bowel disease, and many solid cancers." (PMID 41159061, 2025).
cutaneous melanoma (4 papers, 2021 to 2026). A primary melanoma arising from atypical melanocytes in the skin. "We observed that higher expression of MRC1 was associated with significantly better overall survival in cutaneous melanoma patients." (PMID 35503656, 2022). "We further confirmed a significant positive correlation between MRC1 and C1QC expression in skin cutaneous melanoma patients from the TCGA database." (PMID 35503656, 2022).
helminth infection (4 papers, 2016 to 2025). "We found both Mrc1 and Clec10a to be consistently up-regulated by helminth infections." (PMID 27058578, 2016).
hematoma (4 papers, 2022 to 2026). A hematoma is a collection of blood from a vascular structure into an extravascular space. "Quantification of the hematoma area in four consecutive sections across the primary impact region, ranging from Bregma + 0.14 mm to -1.36 mm, suggested that male MRC1-KO mice exhibited larger hematoma than male MRC1-WT mice." (PMID 41168900, 2025).
infarction (4 papers, 2016 to 2024). A localised pathological necrosis of tissue resulting from obstruction of the blood supply usually by a thrombus, an embolus, or vascular torsion. "The expression level of M2 macrophages markers (Mrc-1, YM-1, CD206, and CCL7) in the infarction and border zones on the 7th day after MI were detected to explore the ability of cardiac repair." (PMID 34214050, 2021).
lung disease (4 papers, 2013 to 2025). "However, in patients resilient to lung disease (no or mild BPD), MRC1 expression increased by day 7 and remained high in later time points." (PMID 32444859, 2020).
Ureteral obstruction (4 papers, 2021 to 2026). Obstruction of the flow of urine through the ureter. "Among macrophage subtypes, infiltrating Ly6ChiChil3+ macrophage and Ly6Clo patrolling macrophages are commonly found in normal kidneys, whereas IFNIC and Mrc1+ macrophages are more common to disease models like unilateral ureteric obstruction model." (PMID 34367152, 2021).
disc degeneration (3 papers, 2021 to 2024). "In contrast, cells expressing the M2 surface marker Mrc1/Cd206 did not associate with disc degeneration in humans." (PMID 36674887, 2023).
keloid (3 papers, 2019 to 2025). An irregularly shaped, elevated mark on the skin caused by deposits of excessive amounts of collagen during wound healing. "Since the downstream genes of RB1 are related with M2 macrophages, for example: C1QC,C1QB,MRC1, fibroblasts in keloid may be beneficial for the transition and proliferation of M2 macrophages." (PMID 35990663, 2022).
lung squamous cell carcinoma (3 papers, 2021 to 2024). "In addition, higher expression of CD163, CD206 (MRC1), and CD11b (ITGAM) in patients with lung squamous cell carcinoma was associated with lower overall survival." (PMID 38521953, 2024).
schizophrenia (3 papers, 2018 to 2022). A major psychotic disorder characterized by abnormalities in the perception or expression of reality. "We also expected to detect no change or decreases in transcripts more often associated with anti-inflammatory microglia/macrophages (CD206 or mannose receptor C1, MRC1, mRNA) as the changes in the midbrain in schizophrenia appear to be more consistent with a tissue-damaging phenotype." (PMID 33133060, 2020).
acute pancreatitis (2 papers, 2012 to 2022). An acute inflammatory process that leads to necrosis of the pancreatic parenchyma. "However, MRC1+ macrophages have not been reported in the study of acute pancreatitis." (PMID 36671463, 2022).
autism (2 papers, 2018 to 2022). Persistent deficits in social interaction and communication and interaction as well as a markedly restricted repertoire of activity and interest as well as repetitive patterns of behavior. "In our study, the combination of Na+, K+, LDH, GST, and MRC1 showed the highest promise in discriminating individuals with autism from controls." (PMID 35260688, 2022).
dementia (2 papers, 2020 to 2023). Loss of intellectual abilities interfering with an individual's social and occupational functions. "The phenotypic transformation from homeostatic microglia towards reactive microglia in dementia pathologies is associated with TREM2, HLA-DRA, ENTPD1 (CD39), CD80 (B7-1), CD86 (B7-2), CCR5, CD274, ITGAX (CD11c), TIMD4 and MRC1." (PMID 33113879, 2020).
E. coli infection (2 papers, 2022 to 2023). "After 24 h of E. coli infection, however, diabetic but not non-diabetic control mice showed significantly higher expression of Mrc1 both on the mRNA and protein levels." (PMID 36127330, 2022).
esophageal cancer (2 papers, 2012 to 2021). A primary or metastatic malignant neoplasm involving the esophagus. "The expression of proinflammatory M1 macrophage genes such as IL1β and TNFα were significantly downregulated in esophageal carcinoma tissues, while M2 marker genes TGFβ1 and MRC1 were upregulated." (PMID 34612767, 2021).
Huntington disease (2 papers, 2019 to 2023). Huntington disease (HD) is a rare neurodegenerative disorder of the central nervous system characterized by unwanted choreatic movements, behavioral and psychiatric disturbances and dementia. "Using a yeast model system, we analyzed the role of Mrc1 and Tof1 at expanded CAG repeats of medium and long lengths, which are known to stall replication forks and cause trinucleotide expansion diseases such as Huntington's disease and myotonic dystrophy." (PMID 30476303, 2019).
nephropathies (2 papers, 2023 to 2025). "The decision tree highlights two proteins (MRC1 and BTD) which, among all the proteins which resulted deregulated in the two groups, could be possible candidates in helping to discriminate IMN disease from other types of nephropathies." (PMID 37511514, 2023). "Finally, the proteomic tree clustering highlighted two proteins (MRC1 and BTD) which, among all the proteins which resulted deregulated in the two groups, could be possible candidates in helping to discriminate IMN disease from other types of nephropathies." (PMID 37511514, 2023).
preeclampsia (2 papers, 2021). Preeclampsia is a hypertensive disorder of pregnancy that is characterized by new-onset hypertension with proteinuria presenting after 20 weeks of gestation, and depending on mild or severe forms may initially present with severe headache, visual disturbances, and hyperreflexia. "M2 macrophages (CD136+MRC1+C1QA+C1QB+, P=0.007) and mast cells (TPSAB1, P=0.007) were decreased in early-onset preeclampsia samples, while M1 macrophages (CD86+MSR1+) were not altered based on gene expression." (PMID 34992598, 2021).
systemic sclerosis (2 papers, 2014 to 2022). A chronic disorder, possibly autoimmune, marked by excessive production of collagen which results in hardening and thickening of body tissues. "However, in PAH associated with systemic sclerosis, macrophage expression of MRC1, as is induced by BMPR2 mutation in the present study, correlates perfectly with development of PAH." (PMID 24713633, 2014).
asbestosis (1 paper, 2025). A lung disorder caused by inhalation of asbestos fibers. "Lung macrophages isolated from humans with asbestosis showed a significant induction in TGFB1, IL10, ARG1, and MRC1 gene expression compared with healthy humans." (PMID 40208691, 2025).
bone tumors (1 paper, 2025). "To further visualize the spatial arrangement of monocytes and TAMs in outgrown bone tumors, we performed multiplex IHC staining in control and ASH1L-depleted tumors using monocyte marker Ly6c, total TAM marker F4/80, and pro-tumoral TAM marker CD206 (encoded by the Mrc1 gene)." (PMID 40394007, 2025).
cleft palate (1 paper, 2024). Cleft palate is a fissure type embryopathy that affects the soft and hard palate to varying degrees. "The MRC1 gene, involved in biological processes such as chemotaxis and leukocyte migration, is associated with cleft palate, another congenital defect, and was expressed in two ToF studies." (PMID 39596121, 2024).
diabetic encephalopathy (1 paper, 2025). A brain disease that is characterized by functional impairment of cognition, cerebral signal conduction, neurotransmission and synaptic plasticity, and underlying structural pathology associated with diabetes. "This study proposes that ceRNA interactions linking lncRNAs NONRATT007456.2, NONRATT020546.2, miR-5132-5p, and MRC1 (mannose receptor C-type 1) contribute to the inflammation-driven pathogenesis of diabetic encephalopathy." (PMID 40421245, 2025).
endotoxemia (1 paper, 2024). "It has been observed that the lack of MRC1 is related to the upregulation of pro-inflammatory cytokines in endotoxemia models." (PMID 39830895, 2024).
head and neck cancer (1 paper, 2020). A primary or metastatic malignant neoplasm affecting the head and neck. "Knockout of miR-21 in Snail-expressing human head and neck cancer cells attenuated M2 polarization of TAMs, and miR-21 was found to be positively correlated with M2 marker MRC1 in head and neck cancer tissues." (PMID 32299469, 2020).
Leber hereditary optic neuropathy (1 paper, 2025). Leber's hereditary optic neuropathy (LHON) is a mitochondrial neurodegenerative disease affecting the optic nerve and often characterized by sudden vision loss in young adult carriers. "Several susceptibility factors have been identified for another optic neuropathy, Leber Hereditary Optic Neuropathy (LHON), caused by mutations in the mitochondrial respiratory complex 1 (MRC1)." (PMID 40722980, 2025).
nephritis (1 paper, 2017). Inflammation of renal tissue. "Expression of both CD11c (Itgax) and CD206 (Mrc1) was increased in control mice with nephritis, and their expression was significantly reduced in Rosa CTGF cKO mice with nephritis." (PMID 28191821, 2017).
nephrotic syndrome (1 paper, 2023). A collection of symptoms that include severe edema, proteinuria, and hypoalbuminemia; it is indicative of renal dysfunction. "In addition, based on a supervised classification tree, two possible candidates (MRC1 and BTD) among the deregulated protein panel showed the ability to distinguish IMN from other nephrotic syndromes with a sensitivity of 93% and a specificity equal to 100%." (PMID 37511514, 2023).
sarcopenia (1 paper, 2022). Progressive decline in muscle mass due to aging which results in decreased functional capacity of muscles. "MRC1 is a biomarker for macrophage relief of cisplatin-induced sarcopenia." (PMID 36419834, 2022).
scrub typhus (1 paper, 2021). Scrub typhus is a rare dust mite-borne infectious disease caused by the Orientia tsutsugamushi bacterium and characterized clinically by an eruptive fever which is potentially serious. "Concurrently, a significant reduction in type 2- or tissue healing-related genes, including Cxcl12 (p < 0.05), Ccrl1 (p < 0.0001), Mrc-1 (p < 0.0001), and Ahr (p < 0.0001), provided additional evidence for skewed type 1, but absent type 2, immune responses in our model of severe scrub typhus." (PMID 34320039, 2021).
T cell deficiency (1 paper, 2022). "In contrast to T cell deficiency, the recurrent tumors were significantly enriched for markers of tumor-associated neutrophils (TANs; eg., CD177, ELANE), tumor-associated macrophages (TAMs; eg., MRC1, CD68), and immune suppressive myeloid cells (MDSCs; eg., ARG1, CXCR4)." (PMID 35919862, 2022).
tonsillar cancer (1 paper, 2018). "This study identified selectively expressed surface markers on specific DC subsets in tonsillar cancer, and CD206/MRC1 and CD207/Langerin on CD1c+ mDCs were confirmed at protein level." (PMID 29795118, 2018).